IGF2BP2 (insulin like growth factor 2 mRNA binding protein 2)
Diseases named in the same sentence as IGF2BP2 in open-access papers (continued):
Sharing a sentence is not in itself a finding about the gene and the disease.
tumor (continued). "In this, we detected high mRNA level of NRP1 in BCa tumor tissues and confirmed that NRP1 level was positively correlated with IGF2BP2 mRNA level." (PMID 39014364, 2024). "Collectively, these studies demonstrate that IGF2BP2 plays a pivotal role in promoting tumor angiogenesis and EMT, both of which are critical for tumor metastasis." (PMID 39596216, 2024). "Therefore, elevated levels of IGF2BP2 may be related to tumor relapse after DDP therapy in LC." (PMID 39731162, 2024). "For instance, in lung cancer, IGF2BP2 increases the stability of fms-related tyrosine kinase 4 (FLT4; also known as VEGFR3) or thymidine kinase 1 (TK1) mRNA, leading to tumor angiogenesis and aggressiveness." (PMID 39098905, 2024). "We identified IGF2BP2 as the most abundant IGF2BP in primary and metastastatic CRC, correlating with tumor stage in patient samples and tumor growth in PDXs." (PMID 37248468, 2023). "IGF2BP2, a member of the IGF2BP family, can mediate post-transcriptional fine regulation of the expression of genes related to tumor cell proliferation, survival, chemoresistance, and metastasis." (PMID 38040698, 2023). "In this context, this study first found that IGF2BP2, a reading protein in m6A, is highly expressed in FLT3-ITD + AML patients and cells, and its regulatory role in tumor progression and glycolysis." (PMID 37060505, 2023). "In conclusion, overexpressed IGF2BP2 in LSCC serves as an oncogenic factor, promoting LSCC cell proliferation and invasion in vitro and tumor growth in a xenograft tumor model in vivo through facilitating CDK6 mRNA stabilization." (PMID 37816718, 2023). "Overall, the current study highlights the markedly upregulated IGF2BP2 levels in HNSCC, which activates PI3K-Akt signaling and plays a pivotal role in promoting tumor cell proliferation." (PMID 37936610, 2023). "However, the role of IGF2BP2 in tumor radiosensitivity remains unclear." (PMID 38042777, 2023). "IGF2BP2, a classical RBP (RNA Binding Protein), has been shown in several studies to be involved in regulating mRNA stability and thus influencing tumor progression." (PMID 38040698, 2023). "The data showed increased expression of IGF2BP2 in HNSCC, which in turn promoted tumor cell proliferation through the phosphatidylinositol-4,5-bisphosphate 3-kinase (PI3K)-protein kinase B (Akt) pathway." (PMID 37936610, 2023). "Mechanistically, FTO acts as a tumor suppressor by inhibiting MTA1 expression, recognized by the m6A reader IGF2BP2, in an m6A-dependent manner." (PMID 37580808, 2023). "Overexpressed IGF2BP2 in LSCC serves as an oncogenic factor, promoting LSCC cell proliferation and invasion in vitro and tumor growth in a xenograft tumor model in vivo through facilitating CDK6 mRNA stabilization." (PMID 37816718, 2023). "As a binding protein of the same type, IGF2BP1, IGF2BP2 and IGF2BP3 interact with same LncRNAs in the same tumor and has the same function." (PMID 37365581, 2023). "For glycan metabolism, multiple m6A methylation regulators (METTL13/IGF2BP2/YTHDF2, etc.)regulate the development of multiple diseases (e.g., tumor and kidney injury) through glycan metabolism." (PMID 35794625, 2022). "We further validated the expression of IGF2BP2 and IGF2BP3 in tumor tissues (COAD, ESCA, and STAD) using qRT-PCR and immunofluorescence staining." (PMID 36686749, 2022). "The expression of IGF2BP2 and MMP9 was upregulated in tumor tissues compared with adjacent normal tissues (P<0.05)." (PMID 36569935, 2022). "Taken together, two tumor antigens (MMP9 and IGF2BP2) were identified as promising candidates for developing mRNA vaccines against BLCA." (PMID 36569935, 2022). "Then, we used UALCAN to further explore the relationship between the mRNA expression of IGF2BP2 and clinicopathological parameters in HNSC patients (age, gender, cancer stages, tumor grades, HPV status)." (PMID 36281789, 2022). "Western blotting was performed to quantify the expression of IGF2BP2 in ESCC cell lines and tumor tissue." (PMID 36364436, 2022).
tumor (continued). "Next, we analyzed the protein levels of IGF2BP2 and IGF2BP3 in different tumor types and normal tissues using the CPTAC dataset." (PMID 36686749, 2022). "Analysis of The Cancer Genome Atlas (TCGA) data combined with immunohistochemical (IHC) tests revealed that IGF2BP2 is over-expressed in HNSCC tissues, promoting scavenging and degradation, synthesis and metabolism and growth of tumor cells." (PMID 33568150, 2021). "Growing evidence has demonstrated that m6A modification is closely associated with tumorigenesis, tumor differentiation, tumor proliferation, tumor invasion and worse survival in BC patients, including METTL3, METTL14, WTAP, ALKBH5, IGF2BP2, IGF2BP3, and FTO." (PMID 33926554, 2021). "This study uncovered that IGF2BP2-mediated m6A methylation was strongly correlated with the malignant progression of HNSCC and tumor immunology signaling pathways." (PMID 33816266, 2021). "Overall, METTL3‐mediated m6A modification contributes to the upregulation of PCAT6 in an IGF2BP2‐dependent manner and the PCAT6/IGF2BP2/IGF1R complex further stabilizes IGF1R mRNA to activate downstream pathways, which promotes BM and tumor growth in PCa." (PMID 34185427, 2021). "We found that the expression of IGF2BP2, RBMX, and HNRNPC was correlated with various activated cancer-related pathways, providing insight into the molecular mechanisms related to tumor progression." (PMID 33816266, 2021). "The results confirmed that IGF2BP2 promoted NCCLC proliferation, as indicated by larger tumor volume and heavier tumor weight." (PMID 35111811, 2021). "In the nervous system, knockdown of IGF2BP2 can significantly reduce FBXL19-AS1 and tight junction related proteins expression, and then promote the permeability of blood-tumour barrier via STAU1-mediated mRNA decay negatively regulating ZNF765 expression." (PMID 34345216, 2021). "Our findings also demonstrated that high expression of IGF2BP2 was related to poor prognosis in LUAD, and the expression of IGF2BP2 was positively correlated with the TNM stage and tumor size." (PMID 35011587, 2021). "Specifically, YTHDF1, IGF2BP2, KIAA1429, RBM15, IGF2BP1, ZC3H13, and METTL3 were significantly up-regulated in tumor tissues by unpaired T-tests (P < 0.05), while ALKBH5, YTHDC2, and METTL14 were significantly down-regulated (P < 0.01)." (PMID 34149792, 2021). "The upregulation of IGF2BP2 mRNA was further validated in fresh NSCLC samples and the paired adjacent non-tumor sites (n = 24, p < 0.01)." (PMID 35111811, 2021). "In summary, this study reveals that m6A‐modified PCAT6 interacts with IGF2BP2 to stabilize IGF1R mRNA, which promotes PCa BM and tumor growth." (PMID 34185427, 2021). "The expression level of IGF2BP2 was, statistically, higher in HNSCC tumor tissues (p = 5.533e-19) compared to adjacent tissues." (PMID 32391379, 2020). "As a result, GHET1, IGF2BP2 and E2F6 presented elevated expression in CC tissues compared with non-tumor tissues." (PMID 31682716, 2020). "An increase in IGF2BP3 expression is associated with increased cell invasiveness and greater dynamics of the tumor process IGF2BP2, in turn, stabilizes IGF-2 mRNA, which increases its expression contributing to tumor development." (PMID 32850012, 2020). "We observed DHX9 and MATR3 (in Tumor A, set 1), HNRNPC and LARP1 (in Tumor A, set 2), SRSF1 (in Tumor B, set 1 & Tumor B, set 2), SRSF6 and IGF2BP2 (Tumor B, set 2), HNRNPU (in Tumor B, set 2 & Tumor C, set 2), and FAM120A and HNRNPA2B1 (in Tumor C, set 2)." (PMID 31892958, 2020). "Clinicopathological correlation analysis showed that upregulation of IGF2BP2 was correlated with tumor grade, TNM stage, and tumor size." (PMID 31852504, 2019). "Putative tumour suppressor genes CDH6 and IGF2BP2 were two of the most significantly fold-decreased genes (p = 0.0003 and p = 5.71 × 10−5 respectively)." (PMID 30513694, 2018).
tumor (continued). "Here, the authors conduct pan-cancer analyses and apply statistical modelling to identify 27 candidate tumour suppressors, including MAFTRR, KIAA1551, and IGF2BP2." (PMID 29089486, 2017). "The expression levels of IGF2BP2, RAI2, SLC25A27, NCBP2, and EIF4B were greatly enhanced, as is the case in tumor development." (PMID 25978455, 2015). "In conclusion, we have demonstrated a novel mechanism by which Lin28b over-expression promotes tumour progression via additional Let-7 gene targets such as CCND2, IGF2BP2, and IGF1R." (PMID 23482325, 2012). "Furthermore, inhibition of IGF2BP2 and RELB suppressed HCC tumor progression both in vitro and in vivo." (PMID 42096134, 2026). "Mechanistically, PRMT1 recruits the SWI/SNF chromatin remodeling complex via direct interaction with SMARCC1, leading to the transcriptional activation of insulin‐like growth factor 2 mRNA‐binding protein 2 (IGF2BP2), which enhances CBP resistance and tumor growth." (PMID 40270464, 2025). "The Venn diagram shows that the expression levels of insulin-like growth factor 2 mRNA binding protein 1 (IGF2BP1), IGF2BP2 and insulin-like growth factor 2 mRNA binding protein 3 (IGF2BP3) were elevated in the tumor microarray data of HBL, and these genes were included in the m6A-related gene list." (PMID 40507253, 2025). "METTL3 also promotes tumor angiogenesis by modifying Ephrin-A receptor 2(EphA2) and vascular endothelial growth factor A (VEGFA) mRNAs with m6A, facilitating their recognition by IGF2BP2/3, stabilizing the mRNA, and enhancing protein translation." (PMID 39791162, 2025). "Nevertheless, we acknowledge that while anti-tumor effects of C4 serve as a proof of principle for the efficiency of pharmacological interference with IGF2BP2 activity for cancer treatment, C4 is not likely to serve as an actual drug for cancer therapy." (PMID 40347943, 2025). "Furthermore, analysis of the TCGA database revealed that IGF2BP2 expression was significantly higher in stage III/IV HCC samples than in stage I/II, and its expression increased progressively with tumor grade." (PMID 39799112, 2025). "Furthermore, high expression levels of IGF2BP2 in OSCC not only promote disease progression but also correlate with cell proliferation, metastasis, and tumor immune cell infiltration, which aligns with our findings." (PMID 40597017, 2025). "IGF2BP2 overexpression promoted tumor growth and reduced CBP sensitivity without affecting body weight." (PMID 40270464, 2025). "Furthermore, PCAT6 enhances IGF1R mRNA stability via the PCAT6/IGF2BP2/IGF1R RNA-protein trimer, thereby upregulating IGF1R expression and promoting PCa bone metastasis and tumor growth." (PMID 38166703, 2024). "Moreover, HE staining revealed obvious necrosis in the tumor tissues of the A549/DDP + DDP group; with even more pronounced necrosis observed following the silencing of IGF2BP2." (PMID 39731162, 2024). "Furthermore, IGF2BP2 was identified as crucial for stabilizing G6PD, promoting tumor growth and metastasis." (PMID 39138186, 2024). "Additionally, the expression of most of the regulators influences the tumor T feature of KIRC, LIHC, PRAD, STAD and THCA, especially IGF2BP1 in BRCA; IGF2BP2, IGF2BP3, LRPPRC, and METTL14 in KIRC; and IGF2BP3 in KIRP." (PMID 39457524, 2024). "IGF2BP2 overexpression in LSCC promotes the CDK6 mRNA stability and protein expression, thus increasing the expression of CDK6 and promoting LSCC cell proliferation and invasion in vitro and tumor growth in xenograft tumor models." (PMID 39403369, 2024). "The Patient-2 tumor sample yielded 453 total cells, with 208 (46%) identified as HGSOC cells, from which we identified 16 different malignant cell enriched fusion transcripts, including the earlier-identified IGF2BP2::TESPA1 fusion between chr3 and chr12 evident in 176/208 (85%) of the tumor cells." (PMID 38464114, 2024).
tumor (continued). "Furthermore, evidence has confirmed that IGF2BP2/3 mediates the pro-angiogenic effects of METTL3 in CRC and, together, promotes tumor progression." (PMID 39033180, 2024). "Accordingly, xenograft assay showed that GAS5 overexpression attenuated tumor growth, while GAS5 silencing promoted tumor growth in vivo, which could be reversed by knockdown or overexpression of IGF2BP2 or QKI." (PMID 38782769, 2024). "By competitively binding to miR-204, lncRNA MALAT1 upregulates IGF2BP2 via m6A modification and enhances MYC expression, thereby stimulating the proliferation, migration, and invasion of TC cells, accompanied by the attenuation of tumor growth and apoptosis." (PMID 39403369, 2024). "The expression of the regulators significantly varies based on tumor stage in a few cancers, including KIRP, KIRC, KICH, LIHC, OV, THCA, and TGCT; IGF2BP2 in KIRC and THCA; IGF2BP3 in KIRP, KIRC, and UCEC; and LRPPRC and METTL14 in KIRC are the ones that are the most varied." (PMID 39457524, 2024). "This suggests that HMGA2 may interact with IGF2BP2 to facilitate the expression of key oncogenes in HCC, contributing to tumor growth and progression." (PMID 39591457, 2024). "Furthermore, IGF2BP2, a potential target gene of MAFG-DT, was found to be overexpressed in tumor tissues and correlated with overall survival (OS)." (PMID 39550498, 2024). "Because both IGF2BP2 and SIRT1 play an important role in tumor, we hypothesize that their mutual regulation also can affect the occurrence and development of ESCC, lncRNA HOXC‐AS1 acts as a molecular scaffold in this progress." (PMID 36510377, 2023). "In addition, IGF2BP2 can bind to TFRC to regulate iron metabolism and enhance tumor growth and proliferation." (PMID 37088822, 2023). "It has been demonstrated that IGF2BP2 is nearly always the most abundant IGF2BP paralogue in human cancers from the TCGA database and was the only IGF2BP member whose expression correlated with late stage tumor growth in the current study." (PMID 37248468, 2023). "In their study, a remarkable IGF2BP2 high expression was observed in TC tumor tissues in comparison with their adjacent noncancerous samples." (PMID 37915103, 2023). "The results of tumor growth curves showed that CSF2 overexpression MSC and P-MSC groups displayed faster tumor growth rates than control MSC groups, while CSF2 knockdown and IGF2BP2 knockdown in P-MSCs markedly reduced the tumor growth rate." (PMID 37865637, 2023). "IGF2BPs, generally including IGF2BP1, IGF2BP2 and IGF2BP3, have also been identified as m6A methyl-binding proteins and they are involved in the stability and degradation of various LncRNAs during the tumor occurrence and development." (PMID 37365581, 2023). "In addition, we showed that GSCAR activates the self-renewal ability of GSCs by mediating DHX9 and IGF2BP2 complex formation, leading to the stabilization of the SOX2 transcript and tumor growth." (PMID 37063420, 2023). "IGF2BP2 and YTHDF1 exerted oncogenic effects on tumor growth and apoptosis inhibition." (PMID 37612282, 2023). "We also found the dependence of STARD14 on RNA methylation levels in LUAD, including the correlation with HNRNPA2B1, IGF2BP2, RBM15 and RBM15, which could participate in the tumor progression of LUAD." (PMID 37790851, 2023). "In addition, PCAT6 enhances IGF1R mRNA stability via the PCAT6/IGF2BP2/IGF1R RNA–protein trimer, thereby upregulating IGF1R expression and promoting PCa bone metastasis and tumor growth." (PMID 38117350, 2023). "The results showed that whilst the positive rate of IGF2BP2 in ESCC tissue reached 96.9% (95/98), the IGF2BP2 expression was not correlated with clinicopathological parameters, such as age, gender, tumor-node-metastasis (TNM) stage and differentiation." (PMID 36364436, 2022). "Tumor growth was significantly inhibited in mice injected with shIGF2BP2, while IGF2BP2 overexpression, but not oe-NC, reversed the shHPV16 E6/E7-induced tumor growth attenuation." (PMID 35002506, 2022).
tumor (continued). "Results indicated that IGF2BP2 was significantly up-regulated in OSCC tumor samples compared with non-tumor tissues." (PMID 35129592, 2022). "The findings of the current study showed that FTO inhibited expression of APOE through IGF2BP2-mediated m6A modification and may inhibit glycolytic metabolism in PTC by modulating IL-6/JAK2/STAT3 signaling pathway, thus abrogating tumor growth." (PMID 35090515, 2022). "Applying phage display techniques, we identified a peptide target for IGF2BP2, which was confirmed to be highly expressed in ESCC cell lines or tumor tissue and may serve as an imaging target for ESCC." (PMID 36364436, 2022). "Our study uncovers a novel molecular mechanism by which the m6A‐induced PCAT6/IGF2BP2/IGF1R axis promotes PCa bone metastasis and tumor growth, suggesting that PCAT6 may serve as a promising prognostic marker and therapeutic target against bone‐metastatic PCa." (PMID 34185427, 2021). "Therefore, the tumor promoter effects of CCAT2 in ESCC are directed by the CCAT2/miR-200b sponging, which limits the miR-200b levels and inhibitory effect on IGF2BP2." (PMID 34830370, 2021). "Furthermore, overexpression of FGF12, FGF14, FGF17, FGFR1, FGFBP3 and IGFBPL1 genes was found in early tumor stage, while, overexpression of IGF1R, IGF2BP2 and INSRR was found in advanced tumor stages." (PMID 34061869, 2021). "Inhibition of IGF2BP2 expression significantly reduces cell proliferation and invasion of NSCLC cells, and IGF2BP2 overexpressed reverses the anti-tumor effects of miR-485-5p in tumor cells." (PMID 34345216, 2021). "In conclusion, this study elucidates a mechanism by which IGF2BP2 promotes DANCR expression and stability through FOXO1 ubiquitination-mediated PID1 expression, thereby promoting cancer cell survival and tumor growth as well as promoting the resistance of GBM cells to etoposide." (PMID 35141227, 2021). "In conclusion, by systematically analyzing the gene expression landscape of 24 m6A regulators in pan-cancer, IGF2BP2 was found to be highly expressed in HNSCC, is correlated with tumor progression and a low survival rate, and is involved in tumor immune invasion." (PMID 33816266, 2021). "Our results furtherly indicated that LINC01001 overexpression accelerates crizotinib-resistant NSCLC cell proliferation, inhibits apoptosis, and accelerates tumor growth via IGF2BP2/MYC axis, indicating LINC01001 regulates crizotinib-resistance NSCLC progression by modulating IGF2BP2/MYC axis." (PMID 34630126, 2021). "In the current experiments, we set about to examine the regulatory effects that IGF2BP2 on GBM cell chemoresistance and analyze the potential regulatory network of the IGF2BP2/DANCR/FOXO1/PID1, aiming to provide a novel antitumor target for tumor treatment." (PMID 35141227, 2021). "These conclusions are urging us to carry out relevant research to verify whether inhibiting the expression of IGF2BP2 and IGF2BP3 can inhibit the growth of the tumor." (PMID 33628845, 2021). "Furthermore, in our subsequent study, we found that IGF2BP2 and TK1 have significantly correlated expression in tumor cells, and our bioinformatics analysis data unraveled that TH1 expression was abnormally elevated in ESCC." (PMID 34386421, 2021). "The subsequent assays revealed a negative correlation between IGF2BP2 and multiple tumor-infiltrating immune cells, such as B cells, CD4+ T cells, follicular helper T cells, and Tregs." (PMID 33816266, 2021). "We found that the copy number loss of ZC3H13, FTO, YTHDC2, WTAP and ALKBH5 decreased the protein expression in tumor samples, and meanwhile, patients with amplification of IGF2BP3, HNRNPA2B1 and IGF2BP2 presented higher expression level of these three proteins than normal tissues." (PMID 32710725, 2020). "Similarly, both of our results confirmed the role of IGF2BP2 and IGF2BP3 in inhibiting tumour progression." (PMID 33246429, 2020).